GSTP1 (glutathione S-transferase pi 1)
Diseases named in the same sentence as GSTP1 in open-access papers (continued):
Sharing a sentence is not in itself a finding about the gene and the disease.
tumor (continued). "The frequency of the methylation in tumour tissue was 57.1% in p16, 2.4% in DAP-kinase, 23.8% in GSTP1, 90.5% in APC, 45.2% in RIZ1, 64.3% in SFRP1, 59.5% in SFRP2, 28.6% in SFRP5, 47.6% in RUNX3, and 54.8% in SOCS1, while in MGMT, no aberrant methylation was detected." (PMID 17968429, 2007). "Although the frequency and levels of GSTP1 methylation were significantly higher than IGFBP3 methylation, an unexpected finding was the concordance between methylation of both genes across all tumours and all but one HGPIN." (PMID 17453001, 2007). "Although there was a significant difference between the methylation levels of GSTP1 and IGFBP3 within tumour samples (P<0.0001; 95% CI=88.17, 174.22), the median RMS of both genes was significantly higher in tumours than in histologically normal adjacent prostate or BPH (P<0.0001)." (PMID 17453001, 2007). "All initial tumor samples (8/8 biopsy specimens) showed GSTP1-HM, including both patients negative for GSTP1 HM in the corresponding RP specimen." (PMID 16803634, 2006). "GSTP1 expression was evaluated in 119 tumour samples (70%), and only three tumours were found not to express this gene." (PMID 16434992, 2006). "The genes APC, MGMT; ER, GSTP1, DAPK, RARβ, FHIT and p16 were evaluated pre and post-treatment for DNA promoter methylation and gene expression by MSP (Methylation-Specific PCR) and RT-PCR respectively in each of the tumor samples." (PMID 15862127, 2005). "Mucinous tumours significantly overexpressed both TYMS and GSTP1 relative to nonmucinous tumours and patient-matched normal mucosa." (PMID 15655543, 2005). "Predominant expression of the GSTP1 subclass (compared to GSTT1 and GSTM1) in colorectal epithelial and tumour tissue may explain in part this phenomenon." (PMID 15213713, 2004). "GSTP1 is a phase II detoxification enzyme that is enriched in mammalian erythrocytes, present in many tumor tissues, and may function via its non-catalytic, ligand-binding activity." (PMID 41301405, 2025). "Our findings also confirm that the hypermethylation of GSTP1 is not restricted to tumor tissues but may also be observed in peripheral blood or other biological samples, highlighting its potential as a non-invasive diagnostic tool." (PMID 40051701, 2025). "In addition, the expression level of GSTP1 in most tumor cells is significantly higher than that in normal tissues, and high expression of GSTP1 is associated with poor prognosis of tumors." (PMID 36589232, 2022). "However, a large number of studies have found that the expression level of GSTP1 in most tumor cells is significantly higher than that in normal tissues, and high expression of GSTP1 is associated with poorer prognosis of tumors." (PMID 36589232, 2022). "Furthermore, although related studies have shown that GSTP1 is closely related to the occurrence and development of tumors, there is no research showing the role of GSTP1 in tumor tissues after radiotherapy." (PMID 34238333, 2021). "The combination treatment did not sensitize the ‘resistant’ or ‘sensitive’ tumor cell lines to cold plasma (EZA vs. EZA + P60s), indicating that GSTP1 mediated s-glutathionylation did not influence the cytotoxic response to cold plasma treatment in tumor cells." (PMID 31931281, 2020). "However, the pattern was only confirmed for GSTM3 in HeLa tumors, while GSTP1 was not detectable in any tumor stage." (PMID 29774096, 2018). "We observed a negative correlation between GSTP1 expression and both tumor size and serum AFP." (PMID 29507666, 2018). "Therefore, an integrated analysis was performed to evaluate the ability of 11 tumor-related genes (p16, CDH1, RUNX3, MLH1, RASSF1A, p15, APC, DAPK, GSTP1, Reprimo, and MGMT) promoter methylation test using blood samples as a feasible biomarker in GC diagnosis and screening." (PMID 29100425, 2017). "A: GSTP1 expression in non-tumor margins; B: GSTP1 expression in tumor." (PMID 28817620, 2017).
tumor (continued). "But DAPK promoter methylation had a similar frequency in the blood in GC and controls, these results suggested that promoter methylation of the ten tumor-related genes (p16, CDH1, RUNX3, MLH1, RASSF1A, p15, APC, GSTP1, Reprimo, and MGMT) may be potential biomarkers based-blood test for GC." (PMID 29100425, 2017). "Besides VHL, other genetic alterations in subgroup-5 involve the mutation of the chromatin remodeling gene PBRM1, the mutation of the histone methyltransferase gene SETD2, which has been identified as a tumor suppressor in KIRC and high methylation rate of GSTP1." (PMID 26148869, 2015). "The rates of GSH-mediated activation of compounds 4 and 5 are enhanced by some human GSTs including GSTM1-1, frequently overexpressed in tumor cells with acquired resistance to nitrogen mustards, while GSTP1-1 had lower or not detectable activity towards these compound." (PMID 24300447, 2013). "In addition ABCB1 methylation was lower in Ki67 positive tumours (P = 0.006) and GSTP1 methylation was lower in PR negative tumours (P = 0.009)." (PMID 20056007, 2010). "Methylation at the ABCB1 or GSTP1 promoter improved overall survival probably due to prolonged availability and activity of the drug in the cell while FOXC1 methylation might be a protective factor against tumour invasiveness." (PMID 20338046, 2010). "In order to improve the response to chemotherapy it seems reasonable that novel small-molecule GSTP1-targeted agents, which were developed to overcome resistance to treatment in ovarian, non-small-cell lung, breast, and colorectal cancers, can also be used to sensitize TCC tumor cells." (PMID 21637416, 2010). "Moreover, we found all CpG sites for RASSF1 and APC, but none for GSTP1, to have significantly higher methylation levels in ER-positive than in ER-negative tumours." (PMID 20565864, 2010). "Both histologic tumour subtypes had higher expression of GSTP1 than the matched normal mucosa." (PMID 15655543, 2005). "Consequently, further investigations suggested that, GSTP1 could be utilized to mediate tumor drug resistance through non-enzymatic pathways." (PMID 39508041, 2024). "Unlike other diseases such as neoplasms in which GSTM1 and GSTT1 polymorphisms are extensively investigated, there are few studies that investigate the association between GSTM1, GSTT1, and GSTP1 gene variants and the presence of microvascular complications in T1DM and T2DM." (PMID 26435566, 2015). "The antioxidant genes NQO1, GSTP1, PRDX1 and NQO1 were upregulated specifically in detached cells, indicating that antioxidant mechanisms were not fully capable of protecting tumor cells against the PDT-inflicted oxidative injuries." (PMID 34371724, 2021). "Proteins that were perturbed in expression level in the peripheral or in the central part of the tumor as compared with the non-involved part included S100A11, HNRNPF, HNRNPH1 or HNRNPH2, GSTP1, PKM and FABP1." (PMID 34563043, 2021). "A correlation study of the methylation proportion of DNA in serum versus cancerous and normal breast tissue revealed a correlation between tumor tissue and serum for BMP6, BRCA1, CST6, GSTP1, P16 and TIMP3 genes but not with the matched normal tissue." (PMID 21283676, 2011). "As another quality control, DNA from the benign tissues used exhibited neither GSTP1 nor RARB2 hypermethylation, excluding contamination with tumor." (PMID 17280610, 2007). "We also wanted to confirm that different levels of WBCs would not introduce more false-positive GSTP1 signals compared to 1000 WBC inputs, since circulating tumor cell samples may have varying levels of WBCs." (PMID 35272673, 2022).
prostate (13 papers, 2004 to 2023). "These pro-oxidative changes in the prostate microenvironment in combination with genetic susceptibility such as defects in encoding for GSTP1 and DNA repair enzymes may contribute to initiation of prostate carcinogenesis." (PMID 24614817, 2014). "Hence, it is possible that the heritable difference in GSTP1 function, due to GSTP1 genetic polymorphism, might be associated with prostate carcinogenesis." (PMID 23977100, 2013). "Low levels of GSTA1 and GSTP1 are suggested to contribute to prostate carcinogenesis." (PMID 28035996, 2016). "Moreover, we reveal a significant correlation of GSTP1 hypermethylation and IGF2-DMR0 hypomethylation suggesting the latter as a conceivable biomarker for prostate carcinogenesis." (PMID 29017567, 2017). "Remarkably, glutathione S-transferase pi 1 (GSTP1), a gene involved in DNA repair, is hypermethylated in more than 90 % of PCa cases, as well as in over 50 % of PCa precursor lesions, suggesting this as an early event in prostate carcinogenesis." (PMID 27651838, 2016).
infection (12 papers, 2009 to 2025). The state of being infected such as from the introduction of a foreign agent such as serum, vaccine, antigenic substance or organism. "GSTT1-null genotype was associated with lymphocytopenia, BLMH rs1050565 G/G genotype was linked with pain in a recessive model of inheritance and GSTP1 rs1695 G/G genotype was associated with infections in a recessive model of inheritance." (PMID 30914949, 2019). "Patients with BLMH rs1050565 G/G genotype experienced severe pain, and patients with GSTP1 G/G genotype were susceptible to severe infections." (PMID 30914949, 2019). "We observed that GSTT1-null genotype is associated with lymphocytopenia (OR = 17.67, CI = 1.23–252.73, p-value = 0.034) and GSTP1 rs1695 G/G genotype is associated with increased infections (OR = 12.25, CI = 1.05–143.09, p-value = 0.046)." (PMID 30914949, 2019). "The BLMH rs1050565 G/G genotype was found to be associated with pain, and the GSTP1 G/G genotype was linked infection (p < 0.05)." (PMID 30914949, 2019). "Considering that glutathione S-transferase P1 (GSTP1) is involved in cellular detoxification, it may play an important role in susceptibility to infection with SARS-CoV-2 and/or its outcome." (PMID 38624527, 2020). "Furthermore, prostate tissue sections showed an increase in the nuclear staining index of oxidative stress-associated marker, 8-OH-dG, and a decrease in GSTP1 expression at 12 and 26 weeks after infection when compared with PBS-control prostate." (PMID 19844236, 2009). "Bearing in mind the Correa cascade, these data could be considered to be in line with our results while underscoring different dominant GSTP1-related molecular mechanisms depending on the infection stage." (PMID 39859205, 2025). "At 6 h post infection, the energy metabolism related genes (ATP5G2, COX17, COX5B, GSTP1, NDUFAB1 and NDUFS2) were suppressed." (PMID 23527143, 2013). "It has been suggested that infection with hepatitis B virus (HBV) or hepatitis C virus (HCV) increases the aberrant methylation of tumor suppressor genes in HCC, including the GSTP1 gene, in HBV-infected HCC but not in non-HBV-infected HCC or in non-HCV-infected HCC." (PMID 22536438, 2012).
peripheral neuropathy (10 papers, 2012 to 2025). A disorder affecting the peripheral nervous system. "In fact, the presence of a well-known genetic polymorphism of GSTP1 (A313G→I105V) was associated with the occurrence of side effects, such as peripheral neuropathy observed in patients with colon cancer." (PMID 37626722, 2023). "Patients with the 105Ile/105Ile GSTP1 genotype had a significantly greater risk of developing more severe docetaxel-induced peripheral neuropathy than did those with other GSTP1 genotypes (P = .03)." (PMID 25596818, 2015). "An association between a GSTP1 polymorphism and docetaxel-induced peripheral neuropathy has also been identified." (PMID 25596818, 2015). "A statistically significant association between the incidence of peripheral neuropathy higher than grade 2 and the GSTP1-105 (P=0.03) and GSTM1 genotypes (P=0.02) was identified by multivariate logistic regression analyses." (PMID 24137384, 2013). "Moreover, a correlation with the severity of peripheral nerve disorders has been suggested on GSTP1 codon 105 polymorphisms." (PMID 28859615, 2017). "In agreement with previous studies, the incidence of peripheral neuropathy higher than grade 2 was identified to significantly correlate with the GSTP1-105 and GSTM1 genotypes." (PMID 24137384, 2013). "A statistically significant correlation between the incidence of peripheral neuropathy higher than grade 2 and the GSTP1-105 (P=0.03) and GSTM1 (P=0.02) genotypes was determined using multivariate regression analysis." (PMID 24137384, 2013). "Therefore, the GSTP1-105 polymorphism may serve as a double-edged marker for predicting response to 5-FU/oxaliplatin treatment and the intensity of oxaliplatin-associated peripheral neuropathy." (PMID 24137384, 2013). "The incidence of peripheral neuropathy of grades 2 (n=42) and 3 (n=2) was found to significantly correlate with the GSTP1-105 (P=0.05) and GSTM1 (P=0.03) genotypes, as identified by univariate regression analyses." (PMID 24137384, 2013). "Peripheral neuropathy occurred in the majority of patients with the GSTP1-105 A/G and G/G genotypes compared with patients with the GSTP1-105 A/A genotype." (PMID 24137384, 2013). "In this way, GSTP1 genotype could be considered a prognostic marker, able to reduce or avoid the peripheral neuropathy." (PMID 37626722, 2023). "In the present study, correlations were identified between the polymorphism patterns of TS, MTHFR, ERCC1, ERCC2, GSTP1, GSTT1 and GSTM1 and the clinical outcome, including the incidence of peripheral neuropathy, in Japanese MCRC patients who were treated with modified FOLFOX6 (mFOLFOX6)." (PMID 24137384, 2013). "Notably, peripheral neuropathy in patients with the GSTP1-105 A/G and G/G genotypes was of greater intensity compared with that of patients with the GSTP1-105 A/A genotype." (PMID 24137384, 2013). "A total of 90 markers in GSTP1, COMT, and TPMT and their adjacent genomic regions (±20 kb) were analyzed for associations with refractory TGCT after first course of chemotherapy, progression-free survival (PFS), overall survival (OS), peripheral neuropathy, and ototoxicity." (PMID 23248619, 2012). "Gene alterations, such as GSTP1 and GSTM1, glutathione-S-transferase genes and voltage-gated sodium channel genes SCN4A, SCN9A and SCN10A, together with pre-existing peripheral neuropathy have been demonstrated to be the principal risk factors for OIPN onset." (PMID 33671327, 2021). "This study examined the association between three genes involved in cisplatin metabolism, GSTP1, COMT, and TPMT, with TGCT outcomes and cisplatin-induced ototoxicity and peripheral neuropathy." (PMID 23248619, 2012). "GSTP1-105 and GSTM1 genotypes may be useful markers of severe peripheral neuropathy in MCRC patients treated with 5-FU/oxaliplatin as first-line chemotherapy." (PMID 24137384, 2013).
peripheral neuropathy (continued). "However, GSTP1-105 and GSTM1 genotypes may be more useful as markers for severe oxaliplatin-induced peripheral neuropathy in Japanese patients compared with Western patients." (PMID 24137384, 2013).
adenocarcinoma (9 papers, 2005 to 2023). A common cancer characterized by the presence of malignant glandular cells. "The percentage of adenocarcinomas from Black patients who had any GSTP1 positive TMA cores was 14.9%, which was 2.5 times higher than the percentage from White patients (5.9%; P < 0.001)." (PMID 34191807, 2021). "Interestingly, in regions of PIA, there appears to be an induction of GSTP1 in luminal cells, which we refer to as intermediate luminal cells; with progression to PIN or adenocarcinoma accompanied by CpG island hypermethylation and loss of expression." (PMID 34191807, 2021). "In the prostate, GSTP1 is constitutively expressed at high levels in basal epithelial cells, variably expressed in luminal epithelial cells, and epigenetically silenced in approximately 90 to 95% of adenocarcinomas by somatic hypermethylation of its regulatory CpG island." (PMID 34191807, 2021). "When the ligand-target links between adenocarcinoma and macrophages were investigated, we identified CALM1, RPS19, GSTP1, and LGALS3 as prioritized adenocarcinoma expressed ligands." (PMID 35954218, 2022).
cardiovascular diseases (5 papers, 2019 to 2023). "Among them, Gstp1 can sensitize cells to free radical-mediated damage by reducing the ability of reactive electrophiles to bind to glutathione, and its main active site is Val105, which is mainly associated with cardiovascular diseases." (PMID 33362553, 2020). "It would be tempting to investigate whether metabolism of ubiquitous reactive aldehyde acrolein, as a typical example of such a GSTP1 substrate associated with increased cardiovascular disease risk, would be affected by GSTP1 polymorphism." (PMID 31275451, 2019). "In the case of cardiovascular diseases, the differences in the influence of GSTM1, GSTT1, GSTP1 and GSTA1 polymorphisms on their development or lack of it depending on the continent were shown." (PMID 37819495, 2023).
neurodegenerative disease (5 papers, 2014 to 2025). A disorder of the central nervous system characterized by gradual and progressive loss of neural tissue and neurologic function. "Reduction in antioxidant glutathione (GSTP1 identified here) may occur in MSA, but peroxiredoxins or CBR1 (both proteins protect from oxidative stress) have not been directly implicated in MSA but have been implicated in other neurodegenerative diseases and neurotoxic insults." (PMID 40122840, 2025).
neurodevelopmental disorder (2 papers, 2024). A behavioral and cognitive disorder with onset during the developmental period that involves impaired or aberrant development of intellectual, motor, or social functions. "All nine children with neurodevelopmental disorders had Hg levels above the safe limit, and eight of them had the GSTP1 rs1695 AA or AG genotypes." (PMID 38922121, 2024).
respiratory disease (2 papers, 2007 to 2008). "GSTP1, the most abundantly expressed member of the GST gene family in the lung, may have a complex impact on respiratory disease." (PMID 17217536, 2007).
heart disease (1 paper, 2020). "Apart from its role in response to oxidative stress and lipid peroxidation, GSTP1 may also affect different signalling pathways, which could contribute to the observed association with heart disease." (PMID 33425072, 2020).
kidney diseases (1 paper, 2019). "The most relevant studies are focused on GSTP1-1 as a biosensor to detect blood toxicity in patients affected by kidney diseases." (PMID 31357662, 2019).
metabolic disorders (1 paper, 2025). "Thus, there is sufficient convincing evidence regarding the probable involvement of the rs1695 GSTP1 polymorphism in the development of metabolic disorders." (PMID 40732231, 2025).
GSTP1 also shares sentences with these, for which no sentence is quoted: renal carcinoma (5 papers); Sepsis (4); idiopathic pulmonary fibrosis (3); mental disorder (3); multiple sclerosis (3); stomach cancer (3); airway hyperresponsiveness (2); Atrophy (2); Burkitt lymphoma (2); colon adenoma (2); cystic fibrosis (2); dental caries (2); depression (2); Hepatic steatosis (2); Hyperglycemia (2); invasive carcinoma (2); papilloma (2); pterygium (2); rheumatoid arthritis (2); systemic sclerosis (2); thoracic tumor (2); thyroid nodule (2); acute liver failure (1); acute myocardial infarction (1); adrenocortical cancers (1); Allergy (1); anaplastic astrocytoma (1); aortic aneurysm (1); autoimmune uveitis (1); basal cell carcinoma (1).
A further 81 diseases each share a sentence with GSTP1 in 1 paper.